NUP98 (nucleoporin 98 and 96 precursor)
Description:
Plays a role in the nuclear pore complex (NPC) assembly and/or maintenance. NUP98 and NUP96 are involved in the bidirectional transport across the NPC. May anchor NUP153 and TPR to the NPC. In cooperation with DHX9, plays a role in transcription and alternative splicing activation of a subset of genes. Involved in the localization of DHX9 in discrete intranuclear foci (GLFG-body). (Microbial infection) Interacts with HIV-1 capsid protein P24 and nucleocapsid protein P7 and may thereby promote the integration of the virus in the host nucleus (in vitro). Binding affinity to HIV-1 CA-NC complexes bearing the capsid change Asn-74-Asp is reduced (in vitro).
Synonyms: Nup96; Nup98-Nup96; Nup98-96; NUP196; ADIR2
Tractability: Antibody: UniProt places it where antibodies can reach, with medium confidence. PROTAC: UniProt records ubiquitination sites on it; ubiquitination databases record sites on it; its protein half-life has been measured.
Gene: Protein-coding gene on chromosome 11 (3,671,083 to 3,797,792, reverse strand). Ensembl gene ENSG00000110713.
Subcellular location: Nucleus membrane; Nucleus, nuclear pore complex; Nucleus, nucleoplasm
Pathways (Reactome):
Disease: Defective TPR may confer susceptibility towards thyroid papillary carcinoma (TPC); HCMV Early Events; HCMV Late Events; NEP/NS2 Interacts with the Cellular Export Machinery; NS1 Mediated Effects on Host Pathways; Nuclear import of Rev protein; Rev-mediated nuclear export of HIV RNA; SARS-CoV-2 activates/modulates innate and adaptive immune responses; Transport of Ribonucleoproteins into the Host Nucleus; Viral Messenger RNA Synthesis; Vpr-mediated nuclear import of PICs
Cell Cycle: Amplification of signal from unattached kinetochores via a MAD2 inhibitory signal; EML4 and NUDC in mitotic spindle formation; Mitotic Prometaphase; Nuclear Pore Complex (NPC) Disassembly; Postmitotic nuclear pore complex (NPC) reformation; Resolution of Sister Chromatid Cohesion; Separation of Sister Chromatids
Metabolism of RNA: Transport of Mature mRNA Derived from an Intronless Transcript; Transport of Mature mRNA derived from an Intron-Containing Transcript; Transport of the SLBP Dependant Mature mRNA; Transport of the SLBP independent Mature mRNA; snRNP Assembly; tRNA processing in the nucleus
Metabolism of proteins: SUMOylation of DNA damage response and repair proteins; SUMOylation of DNA replication proteins; SUMOylation of RNA binding proteins; SUMOylation of SUMOylation proteins; SUMOylation of chromatin organization proteins; SUMOylation of ubiquitinylation proteins
Metabolism: IP3 and IP4 transport between cytosol and nucleus; IP6 and IP7 transport between cytosol and nucleus; IPs transport between nucleus and cytosol; Regulation of Glucokinase by Glucokinase Regulatory Protein
Cellular responses to stimuli: Regulation of HSF1-mediated heat shock response
Immune System: ISG15 antiviral mechanism
Signal Transduction: RHO GTPases Activate Formins
Gene Ontology:
Molecular function: molecular condensate scaffold activity; mRNA binding; promoter-specific chromatin binding; protein binding; structural constituent of nuclear pore; transcription coactivator activity; RNA binding; peptide binding
Biological process: nuclear pore complex assembly; positive regulation of mRNA splicing, via spliceosome; nuclear pore organization; nucleocytoplasmic transport; post-transcriptional tethering of RNA polymerase II gene DNA at nuclear periphery; protein import into nucleus; telomere tethering at nuclear periphery; positive regulation of DNA-templated transcription
Cellular component: kinetochore; nuclear body; nuclear envelope; nuclear inclusion body; nuclear membrane; nuclear periphery; nuclear pore; nuclear pore nuclear basket; nuclear pore outer ring; nucleoplasm; ribonucleoprotein complex; cytosol; nuclear pore cytoplasmic filaments; nucleus
Genetic constraint (gnomAD): Loss-of-function variants: 17 observed, 164.82 expected, observed/expected ratio (o/e) 0.1, 90% interval 0.07 to 0.16. The upper end of that interval is the gene's LOEUF score, 0.16, which puts it in group 1 of 6, group 1 being the genes least tolerant of losing a copy. Missense variants: 1,753 observed, 2,024 expected, observed/expected ratio (o/e) 0.87, 90% interval 0.83 to 0.9. Synonymous variants: 729 observed, 735.97 expected, observed/expected ratio (o/e) 0.99, 90% interval 0.93 to 1.05.
Homologues: Orthologues: chimpanzee NUP98 (99% identical), macaque NUP98 (98% identical), dog NUP98 (93% identical), rabbit NUP98 (93% identical), mouse Nup98 (92% identical), rat Nup98 (91% identical), pig NUP98 (88% identical), guinea pig NUP98 (88% identical), tropical clawed frog nup98 (64% identical), zebrafish nup98 (62% identical), Drosophila melanogaster Nup98-96 (35% identical), Caenorhabditis elegans npp-10 (26% identical).
Diseases named in the same sentence as NUP98 in open-access papers:
NUP98 is named in the same sentence as 69 diseases in open-access papers, as found by Europe PMC text mining. Sharing a sentence is not in itself a finding about the gene and the disease. The quoted sentences say what the papers report.
leukemia (83 papers, 2007 to 2026). A malignant (clonal) hematologic disorder, involving hematopoietic stem cells and characterized by the presence of primitive or atypical myeloid or lymphoid cells in the bone marrow and the blood. "By analyzing representative cases—from the biophysical maturation of TDP-43 in neurodegeneration to the chromatin hijacking by NUP98 fusions in leukemia—we reveal how the loss of "tunable metastability" underpins these disorders." (PMID 41510158, 2026). "In preclinical models, various Menin inhibitors have now shown remarkable effectiveness in treating KMT2A‐rearranged, NPM1‐mutated, and NUP98‐rearranged leukemia." (PMID 39887730, 2026). "In KMT2A‐ as well as NUP98‐rearranged leukemia unbiased CRISPR‐Cas9 screens have revealed that loss of PRC1.1 function renders leukemia cells resistant to Menin inhibition." (PMID 39887730, 2026). "These condensates modulate transcriptional activity and transform hematopoietic stem and progenitor cells, a mechanism extendable to other leukemia-associated NUP98 fusions." (PMID 40442783, 2025). "In instances of human leukemia, recurrent chromosomal translocations give rise to an aberrant chimeric cancer variant featuring NUP98 and HOXA9 proteins." (PMID 38383403, 2024). "NUP98 in human is an essential FG-NUP which is associated with a certain type of leukemia where the FG-repeat domain of NUP98 fuses to a chromatin-binding domain, due to their capacity to concentrate biomolecules, especially oncogenic ones, into condensates." (PMID 39000572, 2024). "Alterations in NUP98, including translocations and mutations, have been associated with various forms of leukemia and other cancers." (PMID 39080077, 2024). "Revumenib treatment blocks leukemic engraftment and prevents leukemia-associated death of immunodeficient mice transplanted with NUP98::NSD1 FLT3-ITD-positive patient-derived AML cells." (PMID 37520776, 2023). "For example, NUP98-HOXA9, a chimera generated by fusion between the DNA-binding domain of HOXA9 (a homeodomain-containing TF) and the FG-repeats-containing segment of NUP98, is associated with development of leukemias." (PMID 36821650, 2023). "NUP98 mutations in leukemias are associated with mutations affecting apoptosis, such as BCR-ABL, NRAS, or KRAS and ICSBP (also known as IRF8)." (PMID 35107131, 2022). "In a mouse model of Nup98-HoxD13-driven leukemia, loss of p300 leads to reduced apoptosis and enhanced activation of JAK/STAT signaling, reminiscent of signaling effects we see in AIP." (PMID 35107131, 2022). "Our work on nucleoporin 98 (NUP98) fusion oncoproteins (FOs) associated with pediatric leukemia inspired us to develop an objective and reliable computational approach for such analyses." (PMID 36304323, 2022). "In leukaemia-associated transcription factor condensates, the Nup98 FG-repeat domain is fused to DNA-binding domains, whereas it is attached to scaffold proteins inside the nuclear pore complex." (PMID 36138110, 2022). "In humans, the normal hematopoietic roles of nucleoporins remains elusive, however several chromosomal translocations into nucleoporin genes, Nup98 in particular, are known to cause a variety of hematopoietic defects and leukemias." (PMID 33561251, 2021). "To date, the NUP98 gene has been implicated in hematopoietic development and found to fuse with more than 30 partner genes and contribute to the onset of leukemia." (PMID 34001105, 2021). "A common feature of leukemias associated with these NUP98 and NUP214 fusions is the overexpression of HomeoboxA (HOXA) genes." (PMID 32343715, 2020). "Further data in support of these findings can be found in a paper exploring the role of Nup98 FG domains, which are recurrent domains of Phenylalanine and Glycine repeats found in Nups, in human leukemia-associated transcriptional upregulation." (PMID 31717499, 2019). "So far, the precise pathogenic mechanism of Nup98- or Nup214-fusion–mediated leukemia still remains to be elucidated." (PMID 31755865, 2019).
leukemia (continued). "Nucleoporin genes, Nup98 and Nup214, are often rearranged in leukemia and generate fusion genes that cause the development of the disease." (PMID 31755865, 2019). "The Nup98-HoxA9 fusion protein has been well studied, and appears to cause leukemia by interfering with the process called (“cell differentiation”) by which stem cells specialize to form different types of blood cells." (PMID 26740045, 2016). "All leukemia-associated NUP98 fusions preserve the GLFG repeats of Nup98, which can act as both transcriptional co-activators through recruitment of p300/CBP and co-repressors through recruitment of HDAC1." (PMID 27031510, 2016). "The gene that produces Nup98 is frequently mutated in leukemia, where part of it becomes fused to regions of other unrelated genes." (PMID 26740045, 2016). "HOXC13 has additional links to leukemia, because fusions of NUP98 and HOXC13 cause human myeloid leukemia." (PMID 27506447, 2016). "Moreover, non‐rearranged KMT2A‐complexes have been demonstrated to be crucial for disease development and maintenance in NPM1‐mutated and NUP98‐rearranged leukemia, expanding the spectrum of genetic disease subtypes that are dependent on KMT2A." (PMID 39887730, 2026). "For instance, targeting NUP98 fusion proteins and their associated proteins with inhibitors that prevent chromatin binding, condensate formation, and oncogene expression represents a potential therapeutic approach for patients with leukemias." (PMID 41099333, 2025). "In addition, mutations in the human nucleoporin NUP98, which provides vital interaction sites for nucleocytoplasmic transport, have been found in hematologic malignancies, including leukemia, and contribute to the fusion of oncoproteins." (PMID 39080077, 2024). "NUP98 mutations contributing to leukemia development have been extensively studied." (PMID 38504158, 2024). "NUP98 fusion proteins are recognized as significant risk factors for leukemia." (PMID 37705755, 2023). "The presence of NUP98 gene fusion defines a high-risk leukemia subset with unfavorable outcomes." (PMID 36959186, 2023). "Self-association and cohesive FG–FG interactions underlie the phase separation and formation of leukaemia-associated Nup98 fusion protein condensates and might influence the mislocalization and accumulation of Nup98 in Alzheimer’s disease." (PMID 36138110, 2022). "Furthermore, mouse models of NUP98-HOX fusions were shown to induce leukemia with variable latency, which was associated with deregulation of HOXA cluster genes that are thought to play a key role in normal hematopoietic differentiation." (PMID 23332017, 2013). "Indeed, type I mutations are common in NUP98 rearranged leukemia, including mutations in the NRAS, KRAS, KIT, WT1 and FLT3 genes." (PMID 23332017, 2013). "Therefore, the misregulation of developmental genes in hematopoietic cells due to genomic fusion of NUP98 with transcription regulators may be a potential mechanism driving the transformation events in NUP98-fusion protein associated leukemias." (PMID 23468646, 2013). "Leukemias with NUP98‐rearrangements express NUP98‐fusion proteins and are associated with a devastating prognosis particularity in children." (PMID 39887730, 2026). "Our data show that CDK12 is crucial for the growth of NUP98::KDM5A-driven leukemia in vitro and in vivo and that small-molecule-mediated perturbation of CDK12 leads to a profound downregulation of genes involved in DNA repair, as reported in previous studies." (PMID 40389480, 2025). "Integration of these data with results from a genome-wide CRISPR/Cas9 screen in NUP98::KDM5A-driven AML cells identifies a core set of 12 essential direct target genes which are critical for the survival of NUP98::KDM5A-driven leukemia cells." (PMID 40389480, 2025). "Future mechanistic studies are warranted to gain profound insights into the role of the NUP98::TNRC18 fusion in leukemia pathogenesis." (PMID 40264981, 2025).
leukemia (continued). "The majority of the 12 essential direct target genes also featured significantly higher H3K27ac marks in human NUP98::KDM5A leukemia cells from a PDX model compared to the mean signal of all other genes in this dataset." (PMID 40389480, 2025). "To gain a better understanding of the epigenetic landscape of NUP98 oncofusion-driven leukemia, we performed ATAC-seq on primary AML patient samples to determine global patterns of chromatin accessibility." (PMID 40389480, 2025). "Preclinical studies have shown that leukemias carrying NUP98-gene rearrangements can potentially be targeted by menin inhibitors." (PMID 39859151, 2025). "Among AML patients, NUP98 fusion-driven leukemia patients (n = 11) showed even higher CDK12 expression, with highest levels detected in NUP98::KDM5A AML (n = 4)." (PMID 40389480, 2025). "Several of the direct NUP98::KDM5A target genes have been described to play roles in leukemia, such as CDKN2C29, CDKN1B30, NKX2-331, IGF2BP332,33, and MN134." (PMID 40389480, 2025). "A recent study by Golovine et al47 has highlighted the significant role of ABL1 kinase in AML1-ETO and NUP98 (nucleoporin 98)-PMX1 (paired related homeobox 1) leukemias." (PMID 40584293, 2025). "In approximately 1–2% of adult AML patients, NUP98 fuses with one of over 30 different partners, contributing to the development of leukemia." (PMID 39590121, 2024). "LNP1 is known to fuse with NUP98 in genome rearrangements of leukemia patients while the 14-3-3 complex is involved with many signaling pathways and associated with cancer." (PMID 39464102, 2024). "Aberrant expression of HOX and MEIS1 family genes, as seen in KMT2A-rearranged, NUP98-rearranged, or NPM1-mutated leukemias leads to arrested differentiation and leukemia development." (PMID 39179671, 2024). "Menin inhibitors hold immense promise for addressing unmet needs in various pediatric leukemia subtypes, including infant KMT2A-r ALL, high-risk KMT2A-r AML, NUP98-r AML, and others." (PMID 39179671, 2024). "Preclinical trials have also shown that mice harboring both FLT3-ITD and NUP98 fusion genes exhibited more aggressive leukemia with a shorter latency period." (PMID 39273530, 2024). "In leukemia patients with NPM1c, or rearrangements in KMT2A and NUP98, a number of these regulators are considered instrumental for loss of transcriptional control and aberrant expression of HOXA/B/MEIS1, and other leukemia-associated target genes." (PMID 38174649, 2023). "Our findings demonstrate that expression levels of FLT3-ITD and also cell proliferation decrease upon ex vivo revumenib treatment of patient-derived NUP98::NSD1/FLT3-ITD+ AML cells suggesting that the NUP98 fusion is the main driver of leukemia development." (PMID 37520776, 2023). "In these murine models, the cooperation between BCR::ABL and the NUP98/HOXA9 gives rise to very aggressive leukemia in mice similar to acute leukemia." (PMID 37174060, 2023). "The human nucleoporin Nup98 forms fusion proteins in certain types of malignant leukaemia, is a critical component of the permeability barrier of the nuclear pore complex and is mislocalized in cytosolic deposits in Alzheimer’s disease." (PMID 36138110, 2022). "In certain types of leukaemia, the FG-repeat domain of Nup98 is fused to a chromatin-binding domain as a result of recurrent chromosomal translocations." (PMID 36138110, 2022). "Chromosomal translocations involving the nucleoporin NUP98 gene are recurrently identified in leukemia; yet, the cellular defects accompanying NUP98 fusion proteins are poorly characterized." (PMID 34831074, 2021). "Studies in mammals have shown that NA9 transformation and leukemia-promoting activity depends on the FG-rich repeats of NUP98 and the DNA-binding activity of the HOXA9 homeodomain." (PMID 34383740, 2021). "Apart from the NUP98 fusions, Hox gene dysregulation has also been associated with MLL fusions, the CALM-AF10 fusion, and NPM1 and IDH1 mutations in leukemia." (PMID 32993115, 2020).